CD163 (CD163 molecule)
Diseases named in the same sentence as CD163 in open-access papers (continued):
Sharing a sentence is not in itself a finding about the gene and the disease.
cancer (continued). "Subsequent analysis of CD86 and CD163 mRNA expression in TAMs cocultured with cancer cells revealed that ANXA2 knockdown increased CD86 expression but suppressed CD163 expression compared with those in the control group." (PMID 39972459, 2025). "In particular, the 3D compartment is composed of a mixed population of CD206 + /CD163+ macrophages and fibroblasts expressing ACTA2/PDGFBRbeta which are known as distinctive for cancer associated fibroblasts." (PMID 40157906, 2025). "As it can be inferred, THCs are identified by the expression of hematopoietic markers, including CD14, CD45 and CD163, provided by the myeloid partner, as well as common cancer-related markers (e.g. cytokeratin or EpCAM)." (PMID 39967663, 2025). "Like cancer, expression of CD163 was significantly related to the CD8+T cells infiltration and macrophages." (PMID 41498045, 2025). "CD163 is strongly expressed on the cell membrane of M2 macrophages and cancer cells in NSCLC 27 Almost all patient samples showed expression of CD163 (98.51%)." (PMID 38616999, 2024). "The CD163 intratumoral average p = 0.01), aggregates (p = 0.01) and touching average (p = 0.001) were significantly higher in cancer tissues." (PMID 38674108, 2024). "Cluster 25 cells (CD163+ApoE+ M2 macrophages) and Cluster 18 (cancer cells) showed the most active cellular interactions." (PMID 39695088, 2024). "CD206 and CD163 are the most frequently used markers of M2-skewed TAMs and are correlated with metastasis and poor disease outcomes in many cancer types, including CRC." (PMID 39516356, 2024). "In conclusion, this study extends our knowledge of the origin of CD163+ TAMs and provides therapeutic insight for targeting them for cancer treatment." (PMID 38903497, 2024). "In all samples, increased CD163+ macrophages (TAMs) were observed around cancer cells, whereas few CD8+ T cells were observed." (PMID 38745748, 2024). "The expression of TF and PDPN in non-cancer cells and CD163-positive monocytes/macrophages was predominantly in the organizing thrombus area." (PMID 40741180, 2024). "Collectively, these findings indicate that the distribution patterns of various immune cell markers, including CD3, CD4, CD8, CD20, CD57, CD68, and CD163, hold potential as prognostic indicators for individuals diagnosed with cancer." (PMID 38730579, 2024). "The abundance of the CD163+ macrophages leads to the proportional elevation of the sCD163 levels in the serum of cancer patients." (PMID 39451197, 2024). "Consistent with previous studies, we confirmed that macrophages co-cultured with cancer cells exhibited high expression of CD163, CD206, Arg1, and IL-10, markers indicative of an M2 phenotype." (PMID 39877420, 2024). "M2 TAMs are involved in the formation of an immunosuppressive microenvironment in advanced cancer, and the present results with CD163‐positive cells confirmed previous findings." (PMID 38978333, 2024). "The mean number and positive area of CD163+ macrophages from three non-cancer parts of peritoneal tissue were 25.7 ± 20.8 and 0.294% ± 0.115%." (PMID 38745748, 2024). "Numerous CD163+ TAMs were observed in the stromal area; however, TAMs were rarely detected in cancer nests." (PMID 36961655, 2023). "In ATCs, TAMs appear to be predominantly polarized toward the M2 phenotype, characterized by CD163 positive staining, expression of pro-tumoral mediators, and secretion of factors that increase cancer cell invasion and stemness." (PMID 37686663, 2023). "Accordingly, CD163 (anti-inflammatory) was significantly downregulated in macrophages from co-culture with C3948 cancer cells." (PMID 37686663, 2023). "As the C1QA-C expression in cancers was mainly detected in CD68+CD163+ macrophages, the synthesis of complement C1q components analysed at the bulk RNA level can potentially be used to estimate the amount of pro-tumoural CD68+CD163+-like macrophages." (PMID 36724681, 2023).
cancer (continued). "In the context of cancer immunity, two important subsets of macrophages have been recognized: M1 (iNOS+) and M2 (CD163+) macrophages." (PMID 37366900, 2023). "Although non-detailed histological subtype was described, an increased density of CD163-positive TAMs either in cancer nests or stroma correlated with poor clinical course." (PMID 37190178, 2023). "The addition of PT-irradiated cancer cells to the macrophage culture increased the expression of the M2 marker CD163 in macrophages in vitro." (PMID 36672266, 2023). "In a previous study, the infiltration of cancer stromal CD163-positive macrophages was examined in ESCC tissues." (PMID 37296952, 2023). "We performed a series of in-depth analyses of single cell RNA sequence data to characterise the origin of the cells identified by CD68 and/or CD163 positivity in cancer tissue." (PMID 36724681, 2023). "In this study, the majority of TNBCs were found to contain at least some cancer cells and CD163+ TAMs expressing detectable PD-L1 although there was considerable heterogeneity in this between tumors." (PMID 38090569, 2023). "In cancer cases, on the other hand, a significant number of LSCCs had TAMs that were positive for CD163 (87% positive tumors, with an IHC score ranging from 1 to 4, χ2=30.634; p<0.001)." (PMID 37082492, 2023). "After 12 weeks, we found that TAM recruitment to the cancer site was significantly increased in mice injected with HER2-overexpressed cancer cells compared to that in mice injected with Vec cells through CD163 staining." (PMID 36674955, 2023). "More CD163+ INHBA+ macrophages were observed in the alveolar cavities of cancer tissues than in normal lung tissues." (PMID 36650150, 2023). "We first investigated the histological correlation between CD163+ TAMs and cancer cells using paraffin-embedded tissue samples from patients with SCLC." (PMID 36961655, 2023). "Multiple immunofluorescence staining displayed the relationship between CD93 expression and CD8, CD68, and CD163 in these cancers." (PMID 36389798, 2022). "Our study provides another piece of convincing evidence to support the effects of CD163 in CRC as well as other types of cancer." (PMID 36551651, 2022). "Further experiments are needed to further confirm the specific regulation at different stages of cancer and the roles and specific functions of CD163 in different pathways." (PMID 36551651, 2022). "We developed a novel algorithm that identifies CD163+ TAMs in an objective manner and quantifies spatial interactions between CD163+ TAMs and cancer cells using distance-based metrics." (PMID 35053472, 2022). "Multiplex immunofluorescence staining showed the upregulated expression level of PDIA5 and the increased number of M2 macrophage markers-CD163 positive cells in pan-cancer samples." (PMID 36003400, 2022). "VSIR was found to co-expression with CD163+ cells in these cancers, including GBM, LSCC, BLCA, CESC, PSCC, and TGCT." (PMID 35493077, 2022). "The expression of pGSN and the relative abundance of HLA-DR+ M1 and CD163+ M2 macrophages in the cancer islet are therefore important factors in determining patients’ sensitivity to treatment." (PMID 35205790, 2022). "These CD163+ TAM metrics as well as the median of the cancer cell-to-CD163+ TAM NND distribution remained significant predictors of PFS in multivariable Cox models adjusted for significant clinicopathological prognostic factors." (PMID 35053472, 2022). "In KIC mice, pancreatic sympathectomy induced an increase in CD163+ macrophage density, which begins during the earliest stages of cancer progression, and later infiltration into PDAC tumors." (PMID 35418199, 2022). "Hybrid cancer cells expressed macrophage-specific antigen CD163, which correlates with poor survival in cancer patients." (PMID 35742997, 2022). "The co-expression of CD147 and macrophage markers CD68 and CD163 in pan-cancer was detected using multiplex immunofluorescence staining on tissue microarrays." (PMID 35464411, 2022).
cancer (continued). "Meanwhile, the two metrics of CD163+ TAM proximity to cancer cells were substantially correlated (coefficient = 0.55; 95% CI: 0.49; 0.62)." (PMID 35053472, 2022). "We developed objective, operator-independent image analysis methods to quantify the density of CD163+ TAMs and explored different spatial metrics of proximity to cancer cells as predictors of clinical outcome." (PMID 35053472, 2022). "ADAMTS1 has been indicated to alter the infiltration of immune cells in B16F1 cancer by increasing CD3+ T cells and CD11b+ myeloid cells with a decreased CD163 expression in ADAMTS1-deficient mice." (PMID 35625488, 2022). "Patients with CD163+ cancer cells are characterized by shorter disease-free survival after radiotherapy." (PMID 35847899, 2022). "Previous reports have indicated that intratumoral CD163+ macrophages are involved in poor prognosis in various cancers." (PMID 36142683, 2022). "The three NND metrics were highly pairwise correlated, but not as correlated with the count and proportion or with the metrics of CD163+ TAM proximity to cancer cells." (PMID 35053472, 2022). "Such more proximal distribution corresponds to a higher prevalence of CD163+ TAMs found next to cancer cells in MMPP." (PMID 35053472, 2022). "The results from public databases show decreased expression of CD163 in cancer tissue compared to normal mucosa (|log FC| > 1 and FDR < 0.01), and it is a negative prognostic factor for CRC patients (p-value < 0.05)." (PMID 36551651, 2022). "The TAM is a macrophage that invades cancer tissue and helps cancer progression, often expresses CD163 and CD206 (markers for M2 macrophages), and produces cancer progression factors, such as VEGF and cytokines." (PMID 34445235, 2021). "Double IHC staining revealed MMP-2 positivity not only in cancer cells involved in lymphatic invasion but also in CD163+ and CD206+ M2 TAMs in all 5 cases." (PMID 33441903, 2021). "Data of Shabo and colleagues revealed that in approximately 48% of breast cancer patients the expression of the macrophage antigen CD163 was found in more than 25% of the cancer cells." (PMID 34572863, 2021). "The expression levels of CD80 and CD86 in U937 cells co-cultured with rapamycin-pretreated cancer cells were increased compared to those of the control group, whereas, CD163 expression was decreased, in both HeLa and SiHa cell co-cultures." (PMID 33390854, 2021). "This suggested that CD163+ mono-macrophage subset was manifested as the phenotype of Tie-2lowCD40high in cancer tissues." (PMID 34803459, 2021). "Similar findings were presented for colorectal tumors, whereby CD163 expression was found in 23% of the patient cancer cells." (PMID 34572863, 2021). "To compare TAM infiltration and PD-L1 expression in human GBM versus a wide range of other cancers, we analyzed the TCGA database for mRNA expression of two TAM-associated genes (CD163; PD-L1 [CD274]) and one T cell-associated gene (CD3E)." (PMID 34083417, 2021). "We showed in a previous report that CD163-positive macrophages infiltrated not only to the cancer nest but also to its surrounding epithelium, depending on the presence of stromal invasion in tongue carcinogenesis." (PMID 34178651, 2021). "For stroma, the marker genes used were VWF, ENG, and CDH5 (for endothelial cells), DCN, ACTA2, and FAP (for cancer-associated fibroblasts), and PTPRC, CD4, and CD163 (for leukocytes)." (PMID 33810510, 2021). "A significant fraction of these cancers contained CD163+pSTAT1Y701+ M1-type Mφ producing CXCL10 and surrounded by CD3 T-cell infiltration." (PMID 34220848, 2021). "Based on our knowledge, there seems to be no study to clearly show the relationship of CD47 expression on cancer cells with stromal CD163+ macrophages." (PMID 33765961, 2021). "It was uncovered that in contrast with para-carcinoma tissues, immune responses of CD163, CD206, and CD11b were much stronger in GC tissues." (PMID 34604066, 2021).
cancer (continued). "A significant increasing trend in the VAP-1+/CD163+ M2 phenotype was observed in cancer specimens for age (p = 0.0164), WHO grade (p < 0.0001), patient survival (p < 0.0001) and IDH mutations (p = 0.0053)." (PMID 32349342, 2020). "Previous evidence suggested that a high density of CD163+ TAMs positively correlated with poor prognosis in many cancer types." (PMID 32509781, 2020). "Although CD163 has been reported a prognostic biomarker in different cancer types, its role in CRC is still unclear and requires further investigation." (PMID 32824692, 2020). "As a prognostic marker in various cancers, understanding the role of CD163-positive TAMs in TME is essential." (PMID 32756500, 2020). "In a drug-development perspective, it would therefore be highly relevant also to investigate CD163 targeting ADCs as a drug delivery system in cancer therapy." (PMID 32752088, 2020). "The use of antibodies for directing anti-inflammatory (e.g., glucocorticoids) or tumoricidal (e.g., doxorubicin) drugs to CD163+ macrophages in animal models of inflammation and cancer has demonstrated a high efficacy of the conjugate drugs." (PMID 32752088, 2020). "It was reported that CD163+ MΦs are distributed not only in the cancer stroma but also within the cancer nest in OSCC." (PMID 31890299, 2019). "The proportion of cancer cells expressing CD163 was higher in NHG3 tumors compared to NHG1 (p = 0.008) and NHG2 tumors (p = 0.06)." (PMID 30915533, 2019). "Patients with malignancies (Group 1) showed increased IL-1β, IL-6, and IL-8 as well as decreased numbers of CD163+ M2 macrophages." (PMID 31366164, 2019). "The isoforms then turn on genes encoding signalling molecules that recruit immunosuppressive CD163+ macrophages and PD-1+ T cells into the cancer." (PMID 31431617, 2019). "Like lymphoid cells, CD68+ and CD163+ macrophages were less abundant in RMS than in the most common cancers of adulthood." (PMID 31239476, 2019). "The distribution of CD163-positive TAMs in cancer tissues was closely related to EMT in Kazakh ESCC." (PMID 31186031, 2019). "Keap-1 knocked-down amplified M2-macrophages induction by cancer cells, appearing as decreased IL-1b and IL-6 expression, and increased CD163 and Arg1 expression." (PMID 30180849, 2018). "Similar to the cancer regions, most MC&M-associated pixels in contact with T cells were CD68+ and CD163+." (PMID 30619287, 2018). "In our study, the cancer cells provoked M2 phenotype as demonstrated by an increase of CD163 and Arg1 and a decrease of IL-1b and IL-6 expression." (PMID 30180849, 2018). "The increase in CD163 expression levels in intratumoral TAM-like cells in HSC-NOG-hIL-6 Tg mice implies that this model is relevant to the clinical course of cancer." (PMID 29456539, 2018). "Logically, the expression of CD163 in cancer cells was also proportional to MI (p = 0.01 between low MI and high)." (PMID 29725763, 2018). "Peripheral blood CD14+ monocytes from healthy donors treated with TRAPs from cancer patients exhibited a significant increase in CD163 and PD-L1 expression and a decrease in HLA-DR expression." (PMID 30563569, 2018). "The CD163+ or M2 macrophage, as a prognosis factor, induce the cancer progression including cancer cell proliferation, migration and invasion, and angiogenesis." (PMID 30180849, 2018). "The low CD163+/CD206+ included the other 5 of the 9 cancer cases with frequencies of CD163/CD206+ pixels less than 3% of the CD163-mask." (PMID 30619287, 2018). "We also verify another two immune checkpoints PD-L1 and CTLA4 have positively correlation with CD163 in cancer cells." (PMID 29152078, 2017). "But cancer cells in subcutaneous, peritoneal and pulmonary had no significantly difference, suggesting CD163 in cancer cells had weak influence on metastasis in nude mice." (PMID 29152078, 2017). "Descriptive pattern of staining for CD163 demonstrated a paucity of M2 differentiation in the benign lymph nodes of cancer-free parotidectomy patients." (PMID 28716144, 2017).
cancer (continued). "CD163 has also been detected in some cancer cells; however these cells are considered as the result of fusion between macrophages and cancer cells." (PMID 28428887, 2017). "The univariate cox analysis also shows that the high expression of CD163 in cancer cells has a significant prognostic impact on overall survival." (PMID 26769084, 2016). "The present study demonstrated that CD68 and CD163 not only express in TAMs, but also in cancer cells." (PMID 26769084, 2016). "The expression of CD68 and CD163 were not only confined to the infiltrating TAMs, but also presented in cancer cells." (PMID 26769084, 2016). "In the present study, we aim to investigate the incidence of CD68 and CD163 in relation to clinicopathological features and outcomes, then further insight into the interaction between TAMs and cancer cells undergoing EMT in OSCC progression." (PMID 26769084, 2016). "Cancer patients expressed higher mRNA levels of the M2 polarization markers CD163, ARG1 and IL-10 in CD11b+ cells and increased levels of the M2 cytokines IL-10 and CCL20 in plasma." (PMID 26840567, 2016). "The genesis of CD163 expression as a macrophage trait in cancer cells reported in previous clinicohistopathological studies is unclear." (PMID 26585897, 2015). "On the other hand, CD163 expression was barely detectable in peripheral blood from both cancer and non-cancer patients." (PMID 25871392, 2015). "CD163 staining was scored on a 5-tiered score as follows: 0 %, 1–25 %, 26–50 %, 51–75 %, and 76–100 % of the cancer cells." (PMID 26585897, 2015). "The histopathological analysis in this study clearly shows that CD163-positive cancer cells are organized in a growth pattern of one or more collections." (PMID 26585897, 2015). "In all the studies expression, the level of CD163 on the cancer cells correlated with poor survival." (PMID 26111002, 2015). "The proportion of CD163 positive cancer cells was greater than 50 % in 34 (47 %) of the total of 72 positive tumors." (PMID 26585897, 2015). "CD163 positive cancer cells were organized in a growth pattern of one or more groups or clonal collections." (PMID 26585897, 2015). "CD163 expression on the cancer cells has been demonstrated in 48% of breast cancer biopsies, 39% of bladder cancer biopsies, 23% of rectal cancer biopsies and 20% of colorectal cancer biopsies." (PMID 26111002, 2015). "In the present study, we showed the level of MDSCs in PBMC and Arg1 in plasma were significantly elevated in ECA patients, and the increased ratio of MDSC in PBMC was closely related to the expression of CD163 in cancer tissues." (PMID 25144454, 2014). "We observed that the protein expression of the TAM markers CD68 and CD163 as well as the cancer stem cell (CSC) markers ALDH1, CD44, and SOX2 increased successively from the normal oral mucosa to OSCC." (PMID 24883329, 2014). "ix) Finally, localization of CD68+ (H2) and CD163+ (I2) macrophages close to carcinoma cells as well as high expression of FoxP3 (O2), L1CAM (P3) and vimentin (R), respectively, tended to be associated with higher grading (S)." (PMID 24797069, 2014). "Like in the EL4 cancer model, this therapeutic effect was correlated with the depletion of CD163+ M2-type TAMs." (PMID 24019914, 2013). "Both NOS2 and CD163 have been utilized by others as markers to define M1 or M2 macrophage phenotypes in human cancers." (PMID 23077543, 2012). "To assess the prognostic impact of macrophage infiltration, we compared overall cancer-specific survival in patients with different scores of infiltrating NOS2+ or CD163+ macrophages." (PMID 23077543, 2012). "We found down-regulation of the pro-inflammatory CD163 in macrophages grown as co-culture with cancer cells." (PMID 22353646, 2012). "CD163 has been identified as a potential biomarker for ICI therapy in patients with cancer." (PMID 40075727, 2025).